NOTCH3 (notch receptor 3)
Diseases named in the same sentence as NOTCH3 in open-access papers (continued):
Sharing a sentence is not in itself a finding about the gene and the disease.
preeclampsia (3 papers, 2015 to 2017). Preeclampsia is a hypertensive disorder of pregnancy that is characterized by new-onset hypertension with proteinuria presenting after 20 weeks of gestation, and depending on mild or severe forms may initially present with severe headache, visual disturbances, and hyperreflexia. "The expression of Notch2 is decreased, and that of Notch3 is generally increased, in the placental tissues from patients with preeclampsia compared to those with normal placental tissues, according to previous experiments." (PMID 28606936, 2017). "The results of a previous study showed an obvious upregulation of Notch3 expression, and a downregulation of Notch2 expression, in placentas from patients with early onset severe preeclampsia compared with those in normal placentas." (PMID 28606936, 2017). "It is hypothesized that abnormal expression of Notch2 and Notch3, and the resulting effects on trophoblast cells, might lead to the early onset of severe preeclampsia and other obstetric disorders." (PMID 28606936, 2017). "Previous research showed that Notch2 expression decreased, and Notch3 was overexpressed, in the placentas of patients with preeclampsia compared with normal placentas, which indicate that Notch2 and Notch3 may play important roles in the pathology of preeclampsia." (PMID 28606936, 2017). "Taken together, our study results provide evidence that Notch2 and Notch3 are able to suppress proliferation by inducing cell cycle arrest, and promote the migration and invasion of trophoblast cells, through which they might participate in the pathogenesis of preeclampsia." (PMID 28606936, 2017). "However, the mechanisms by which Notch2 and Notch3 are related to preeclampsia remain unknown." (PMID 28606936, 2017). "Notably, it has experimentally validated interactions with a number of genes known to be directly involved in the pathology of preeclampsia, particularly at the placenta: VEGF, NOTCH-3, IGF-1 and hypoxia inducible factor 1 α (HIF-1α)." (PMID 26213997, 2015).
prostate tumor (3 papers, 2013 to 2015). "Prostate was the most frequently mutated cell type for both NOTCH1 and NOTCH2 but prostate tumor cell lines did not contain any mutations in NOTCH3 or NOTCH4 (right hand side)." (PMID 25907971, 2015). "Moreover, we have shown that endothelial Jagged1 regulates prostatic tumor cell proliferation and de-differentiation by activating Notch3 and consequently up-regulating Hey1 in tumor cells." (PMID 26213336, 2015).
renal fibrosis (3 papers, 2020 to 2025). A final common manifestation of a wide variety of chronic kidney diseases characterized by glomerulosclerosis and tubulointerstitial fibrosis. "In the rat model of UUO, which mimics human disease, Notch3 upregulation closely followed the processes of renal injury, renal fibrosis, TGF-β expression, and α-SMA expression." (PMID 33149805, 2020). "Additionally, Notch3 seems to have a role in the progression of renal fibrosis, which is evidenced by the knockout of Notch3 shown to have protective effects on fibrosis development with the smaller number of alpha SMA staining cells." (PMID 41074478, 2025). "Accumulating evidence supports a role of Notch3 in renal fibrosis." (PMID 33149805, 2020). "The high expression of TGF-β-Notch3 has been shown to be an important factor in promoting renal fibrosis, and inhibition of the Notch3 expression might be an effective therapeutic approach to alleviate renal interstitial fibrosis." (PMID 33149805, 2020). "Interestingly, a recent scRNA-seq study in renal fibrosis resolved a differentiation path from NOTCH3+ pericytes to myofibroblasts suggesting this subset may be a conserved precursor across diverse fibrotic disorders." (PMID 35320046, 2022). "Additionally, Notch3 may interact with other renal fibrosis signaling molecules." (PMID 33149805, 2020).
viral infection (3 papers, 2022 to 2025). "Six genes were closely associated with viral infection, namely, LY6E, receptor-type tyrosine-protein phosphatase S (PTPRS), neurogenic locus notch homolog protein 3 (NOTCH3), tripartite motif containing 56 (TRIM56), ring finger protein 135 (RNF135), and growth arrest-specific 6 (GAS6)." (PMID 38169284, 2024). "We identified 31 differentially expressed circRNAs and 7 mRNAs (HSPA8, HSPA1B, EGR2, CXCR4, SOCS3, NOTCH3, and ZNF527) related to viral infection." (PMID 41471859, 2025).
acute kidney injury (2 papers, 2023 to 2025). Sudden and sustained deterioration of the kidney function characterized by decreased glomerular filtration rate, increased serum creatinine or oliguria. "Targeting NOTCH3 could offer a novel therapeutic approach for acute kidney injury." (PMID 37667551, 2023). "NOTCH3 targeting could offer a novel therapeutic approach for acute kidney injury." (PMID 37667551, 2023).
brain arteriovenous malformations (2 papers, 2015 to 2023). "We have found that compared to normal brain vascular tissue Notch-3 was dramatically increased in brain arteriovenous malformations." (PMID 25846406, 2015). "While NOTCH3 signaling in regulating vascular smooth muscle cell differentiation has been widely reported, a possible role of NOTCH4 in contributing to the pathogenesis of brain arteriovenous malformations has been described only in mice." (PMID 37063679, 2023).
cardiomyopathies (2 papers, 2020 to 2021). "Moreover, interactions among DAB1 or NOTCH3 and respective proteins using the STRING database suggested the potential effects on the development of cardiomyopathies." (PMID 34222332, 2021).
chronic lung disease (2 papers, 2021 to 2022). According to the definitions of the American and British Thoracic Societies, including pulmonary functional tests, X-rays, and CT scans for items such as fibrosis, bronchiectasis, bullae, emphysema, nodular or lymphomatous abnormalities. "Therefore, a greater understanding of the downstream genes and pathways that regulate NOTCH3-dependent differentiation is critical for understanding the mechanisms driving airway epithelial remodeling associated with chronic lung disease." (PMID 34831437, 2021). "Evidence provided in this review highlights the involvement of NOTCH3 signalling in the development of acute and chronic lung disease." (PMID 36052538, 2022). "Despite the knowledge NOTCH3 signalling is not essential for murine lung development, there is emerging evidence that dysregulation of NOTCH3 signalling in the adult human lung plays an important role in the development and pathogenesis of acute and chronic lung disease." (PMID 36052538, 2022).
emphysema (2 papers, 2020 to 2022). "This study indicates that Notch3 signaling contributes to pulmonary emphysema in mgR mice." (PMID 32616814, 2020). "However, the mechanism by which Notch3 exerts its function in pulmonary emphysema in MFS remains unknown." (PMID 32616814, 2020). "Inhibition of Notch3 signaling may attenuate pulmonary emphysema in MFS." (PMID 32616814, 2020). "Therefore, we investigated whether Notch3 signaling plays a role in pulmonary emphysema in MFS." (PMID 32616814, 2020).
frontotemporal dementia (2 papers, 2022 to 2025). Frontotemporal dementia (FTD) comprises a group of neurodegenerative disorders, characterized by progressive changes in behavior, executive dysfunction and language impairment, as a result of degeneration of the medial prefrontal and frontoinsular cortices. "Frontotemporal dementia (FTD) has been linked to mutations in MAPT and GRN, while vascular dementia has been linked to NOTCH3 polymorphisms that compromise vascular integrity." (PMID 40559997, 2025). "These variants map to the CCNF, DCTN1, and NOTCH3 genes, which are involved in the ALS/frontotemporal dementia (FTD) spectrum." (PMID 36133075, 2022).
gastric adenocarcinoma (2 papers, 2020 to 2025). "Univariate Cox regression analysis demonstrated NOTCH3 as an indicator for poorer overall survival in patients with stomach adenocarcinoma (STAD), as well as multiple other malignancies." (PMID 40940884, 2025). "In Chen’s dataset, the expression of Notch3 in gastric adenocarcinoma was 1.594 and 1.871 times respectively of that in the samples of normal tissue." (PMID 32028262, 2020). "High Notch3/4 expression was associated with high levels of infiltration of macrophage and CD4+ T cells in gastric adenocarcinoma." (PMID 32028262, 2020). "The expression of Notch1, Notch2, Notch3 and Notch4 proteins, which were examined by immunohistochemistry, were higher in the gastric adenocarcinoma tissues than that in the normal gastric tissues." (PMID 32028262, 2020).
glomus tumor (2 papers, 2025). A rare benign or malignant mesenchymal neoplasm arising from cells that resemble the modified smooth muscle cells of the glomus body. "Familial occurrences of glomus tumors suggest a genetic predisposition, with mutations in genes such as NOTCH3 and PDGFRB implicated in some cases, though the complete genetic landscape remains incompletely understood." (PMID 39776317, 2025). "Recent reports have identified PDGFRB and NOTCH3 mutations as characteristics of myopericytoma; however, these mutations have also been observed in angioleiomyoma and glomus tumors, suggesting that they are not useful for differential diagnosis." (PMID 40599523, 2025).
hyperplasia (2 papers, 2019 to 2022). An abnormal increase in the number of cells in an organ or a tissue with consequent enlargement. "Also, increased NOTCH3 expression may be related to the elevated endometrial thickness and hyperplasia that is seen in women with PCOS." (PMID 31168348, 2019).
imbalance (2 papers, 2022 to 2026). "The results demonstrated more prevalent motor symptoms in NOTCH3-variant carriers, especially more severe in stiffness (p = 0.278), bradykinesia (p = 0.547) and postural instability (p = 0.119)." (PMID 36570541, 2022).
infantile hemangioma (2 papers, 2016 to 2021). "We previously observed that NOTCH3 is expressed in the immature ECs of infantile hemangiomas (IH), a blood vascular anomaly." (PMID 34043714, 2021). "Interestingly, some of these genes also play roles in cell signaling pathways that have been linked to the pathogenesis of infantile hemangioma; namely, VEGFA in the VEGF/VEGFR pathway, ANGPT2 and ANGPTL1 in the Tie2/Angiopoietin signaling pathway and NOTCH3, NOTCH4 and JAG1 in the Notch pathway." (PMID 26772808, 2016).
inflammatory breast carcinoma (2 papers, 2014 to 2020). An advanced, invasive breast adenocarcinoma characterized by the presence of distinct changes in the overlying skin. "High activity of Notch3 signaling was associated with aggressive human inflammatory breast cancer and increased lymphovascular invasion, again suggesting tumorigenic activity of Notch3." (PMID 25229616, 2014). "For example, Sdc-1 expression in inflammatory breast cancer is correlated with CD44, Notch-1, and Notch-3 expression, and siRNA knockdown of Sdc-1 results in a weaker CSC phenotype and reduced expression of Notch-1-4 and Hey1 in inflammatory breast cancer cells." (PMID 33102470, 2020).
invasive breast carcinoma (2 papers, 2021 to 2023). A carcinoma that infiltrates the breast parenchyma. "Based on the dataset from TCGA, for 817 patients with breast invasive carcinoma, the expression of Notch3 was positively associated with the levels of STAT5A (p = 0.001 and Spearman r = 0.1154)." (PMID 38124049, 2023). "Notably, we also find the expression level of STAT5A to be positively related to Notch3 expression in patients with invasive breast carcinomas." (PMID 38124049, 2023). "ONCOMINE analysis revealed that Notch3 and PTEN mRNA expression levels were both significantly higher in invasive breast cancer than in normal tissue in the Finak Breast dataset." (PMID 34006834, 2021).
invasive ductal carcinoma (2 papers, 2021). "Therefore, we evaluated the relationships between Notch3 and PTEN expression and the pathological parameters of 250 human invasive ductal carcinoma tissue samples." (PMID 34006834, 2021).
leukoaraiosis (2 papers, 2019 to 2020). "If we assume that the temporal pole is less vulnerable to leukoaraiosis than the other brain regions, this might be explained by the different tendencies of NOTCH3 protein accumulation around vascular smooth muscle cells between cysteine-involving and cysteine-sparing mutations." (PMID 32555735, 2020).
liver cirrhosis (2 papers, 2017 to 2021). "Finally, the NOTCH3 rs1043996 GG genotype was associated with a lower susceptibility to liver cirrhosis in a recessive model (OR 95%CI = 0.39 (0.19–0.80, p = 0.01)." (PMID 34640639, 2021). "The target gene of miR-34c-5p is the important profibrotic factor NOTCH3, which activates HSCs to promote the development of liver cirrhosis." (PMID 28355233, 2017).
metastatic melanoma (2 papers, 2018 to 2019). A melanoma that has spread from its primary site to another anatomic site. "Therefore, the herein identified MMP14 dependent Notch3 upregulation may prove important in metastatic melanoma progression." (PMID 29712618, 2018).
myeloid leukemia (2 papers, 2011 to 2013). A clonal proliferation of myeloid cells and their precursors in the bone marrow, peripheral blood, and spleen. "This tumor suppressive properties are consistent with recently reported role of Notch pathway in myeloid leukemia and confirm prior results on the tumor suppressive nature of Notch signaling, including Notch3, in B cell malignancies." (PMID 23637910, 2013). "This minireview focuses on recent advances related to the mechanisms and roles of activated Notch1, Notch2, Notch3 and Notch4 signaling in human lymphocytic leukemia, myeloid leukemia and B cell lymphoma, as well as their significance, and recent advances in Notch-targeted therapies." (PMID 22128846, 2011).
ovarian disease (2 papers, 2012 to 2026). "To further explore the clinical relevance of DLK1 and NOTCH3 expression alterations, we investigated their levels in ovarian diseases, specifically POI." (PMID 41243550, 2026). "Anecdotal evidence includes altered regulation of Notch3 in chemoresistant ovarian disease and the clear parallel between epithelial-mesenchymal transition (EMT) and CSC differentiation mechanisms." (PMID 22260314, 2012).
pancreatic ductal adenocarcinoma (2 papers, 2017 to 2024). An infiltrating adenocarcinoma that arises from the epithelial cells of the pancreas. "Notch3 also induces the formation of metastatic foci in pancreatic ductal adenocarcinoma cells through MMP2 (Matrix Metalloproteinase 2) and MMP9 (Matrix Metalloproteinase 9)." (PMID 38782818, 2024).
renal cell carcinoma (2 papers, 2022). "Whole-exome sequencing of patients with tuberous sclerosis complex-associated renal cell carcinoma and microarrays in different types of renal tumors also revealed increased Notch3 expression in neoplastic tissue." (PMID 35055068, 2022). "This led us to analyze the expression of Notch3 in major renal cell carcinoma subtypes and to reanalyze available public data." (PMID 35055068, 2022). "Our results show an increased upregulation of Notch3 in various renal cell carcinomas." (PMID 35055068, 2022). "This pathological process occurs because aberrant Notch3 signaling influences proliferation, the alignment of cell division and dedifferentiation in the proximal and distal tubules, thus favoring the progression of cystic renal diseases and eventually the development of renal cell carcinoma." (PMID 35055068, 2022). "A main finding was a significant upregulation of Notch3 in epithelial cells of all PKD cases and renal cell carcinomas." (PMID 35055068, 2022). "On the other hand, activation of Notch3 did not induce renal cell carcinoma in our animal model, suggesting either a second hit or longer duration of activation is necessary for the development of RCC." (PMID 35055068, 2022).
Sneddon syndrome (2 papers, 2015 to 2021). Sneddon's syndrome (SS) is a rare non-inflammatory thrombotic vasculopathy characterized by the combination of cerebrovascular disease with livedo racemosa. "Intriguingly, a classical NOTCH3 CADASIL-causing mutation had been associated with Sneddon syndrome." (PMID 25870235, 2015).
urothelial carcinoma (2 papers, 2017 to 2018). A malignant neoplasm derived from the transitional epithelium of the urinary tract (urinary bladder, ureter, urethra, or renal pelvis). "Another mechanism was expression of the hypoxia-regulated Notch3 gene, which causes chemotherapy resistance in urothelial carcinoma, although the mechanism is unknown." (PMID 30555629, 2018). "Taken together, Notch3 overexpression enhances growth and chemoresistance in urothelial carcinoma, indicating that Notch3 protein levels may serve as a prognostic marker in human urothelial cancer." (PMID 28416766, 2017).
Ventricular hypertrophy (2 papers, 2023 to 2025). Enlargement of the cardiac ventricular muscle tissue with increase in the width of the wall of the ventricle and loss of elasticity. "Notably, the pro-ventricular hypertrophy effect of Notch2 is quite different from the functions of Notch1 and Notch3 in cardiac development, since mice lacking each of them develop HCM." (PMID 40104444, 2025).
abortion (1 paper, 2023). the ending of pregnancy by removing a fetus or embryo before it can survive outside the uterus. "qPCR was performed in placentas and the results showed decreased Jag1, Notch3 and Hes1 mRNA levels in LPS‐induced abortion mouse model compared with the control (n = 3/group)." (PMID 37272232, 2023). "In addition, GDF15 could serve as a pro‐invasive factor in human extravillous trophoblasts and upregulate JAG1/NOTCH3/HES1 pathway activity as well as rescue the embryo absorption phenotype observed in the LPS‐induced abortion mouse model." (PMID 37272232, 2023).
ameloblastoma (1 paper, 2020). The most common odontogenic tumor, arising from the epithelial component of the embryonic tooth and usually affecting the molar-ramus region of the mandible or maxilla. "NOTCH3 expression partially overlapped with that of NOTCH2, as it was detected at the interface between the ameloblastoma epithelium and the underlying stroma." (PMID 32155948, 2020). "Expression of NOTCH2 and NOTCH3 was associated with expression of the ligands JAG1, DLL1, and DLL4 in the ameloblastoma epithelium." (PMID 32155948, 2020). "We observed that NOTCH3, JAG1, DLL1, and DLL4 are also expressed within the ameloblastoma tumor mass." (PMID 32155948, 2020). "NOTCH3 was also detected within the ameloblastoma epithelium, where NOTCH3 expressing regions were irregularly alternated with NOTCH3 negative areas." (PMID 32155948, 2020). "Here, we showed that NOTCH2 and NOTCH3, but not NOTCH1 (data not shown), are expressed at the interface between the ameloblastoma epithelium and the underlying stroma, which is a location pivotal for the acquisition of an invasive phenotype." (PMID 32155948, 2020).
ampullary cancer (1 paper, 2015). "The Notch pathway is located upstream of nestin and the NOTCH2 and NOTCH3 genes were overexpressed in ampullary cancer." (PMID 25371063, 2015).
amyloidosis (1 paper, 2005). A disorder characterized by the localized or diffuse accumulation of amyloid protein in various anatomic sites. "Misfolding of transthyretin (meningovascular amyloidosis), angiotensinogen, β2 – microglobulin, lysozyme, the Notch3 gene product, and the familial prion protein may each lead to amyloidosis." (PMID 16321154, 2005).
Anxiety (1 paper, 2025). Intense feelings of nervousness, tension, or panic often arise in response to interpersonal stresses. "Genes like CACNA1C (calcium regulation) and AHR (inflammation) may influence pain pathways, while NOTCH3 is involved in immune responses and stress regulation, and anxiety may contribute to pain modulation." (PMID 39940809, 2025).
aortic stenosis (1 paper, 2022). Aortic valve stenosis is a aortic valve disease caused by the incomplete opening of the aortic valve. "In addition, genetic deletion of Notch3 significantly reduces aortic stenosis in Eln–/– mice and hypermuscularization in both Eln+/– and Eln–/– mice." (PMID 34990407, 2022).